RECQL4 (RecQ like helicase 4)
Diseases named in the same sentence as RECQL4 in open-access papers (continued):
Sharing a sentence is not in itself a finding about the gene and the disease.
Baller-Gerold syndrome (32 papers, 2010 to 2025). Baller-Gerold syndrome is characterized by the association of coronal craniosynostosis with radial ray anomalies (oligodactyly, aplasia or hypoplasia of the thumb, aplasia or hypoplasia of the radius). "Pathogenic variants in RECQL4 are clinically associated with 3 rare autosomal recessive conditions: Rothmund-Thomson syndrome type II, Baller-Gerold syndrome, and RAPADILINO syndrome." (PMID 40819286, 2025). "In humans, ESCO2, TBX5, and RECQL4 cause Roberts, Holt–Oram, and Baller–Gerold syndromes, respectively." (PMID 34249098, 2021). "RTS and the related RAPADILINO and Baller-Gerold syndromes are associated with damaging germ-line mutations in RECQL4." (PMID 31276497, 2019). "We report here that during unperturbed cell proliferation, dormant origins selectively bind phosphorylated RecQL4 (pRecQL4), a member of the RecQ helicase family mutated in Rothmund-Thomson, RAPADILINO and Baller-Gerold syndromes." (PMID 40319014, 2025). "Mutations in the RecQL4 gene are linked to several rare genetic disorders, including Rothmund-Thomson syndrome, RAPADILINO syndrome, and Baller-Gerold syndrome." (PMID 40319014, 2025). "Loss of function mutations in RecQ like helicase 4 (RECQL4) are linked to different autosomal recessive and cancer‐prone syndromes such as Rothmund–Thomson syndrome, Baller–Gerold syndrome and RAPADILINO." (PMID 39812592, 2025). "Biallelic variants in RECQL4 have been associated, besides RTS, with two other distinct phenotypes, RAPADILINO and Baller-Gerold syndromes." (PMID 38021400, 2023). "More than 100 variants have been reported in RECQL4 in individuals presenting mainly RTS, and less frequently, RAPADILINO and Baller-Gerold syndromes." (PMID 38021400, 2023). "Homozygous or compound heterozygous germline mutations in the RECQL4 gene are linked to the recessive syndromes Rapadilino syndrome (RAPADILINO syndrome; OMIM #266280) and Baller–Gerold syndrome (BGS; OMIM #218600)." (PMID 37762649, 2023). "Other syndromes caused by variants in RECQL4 include RAPADILINO syndrome and Baller-Gerold syndrome." (PMID 35782872, 2022). "Mutations in RECQL4 are associated with three rare autosomal-recessive disorders: Rothmund–Thomson syndrome (RTS; OMIM #268400), RAPADILINO (RAPA; OMIM #266280), and Baller–Gerold syndrome (BGS; OMIM #218600)." (PMID 33718381, 2021). "Mutations in the RECQL4 gene have been found in the majority of RTS patients, and also in the related RAPADILINO and Baller-Gerold Syndromes." (PMID 31276497, 2019). "Mutations in RecQL4 helicase results in three clinically related autosomal recessive disorders: Rothmund–Thomson syndrome (RTS), RAPADILINO, and Baller–Gerold syndrome." (PMID 30206236, 2018). "RECQL4 mutations are associated with Rothmund Thomson Syndrome (RTS), RAPADILINO Syndrome and Baller-Gerold Syndrome." (PMID 25859855, 2015). "Two other syndromes are also associated with mutations of the RECQL4 gene, RAPADILINO, and Baller-Gerold syndrome." (PMID 26617641, 2015). "In humans, mutations of RECQL4 are associated with a series of related syndromes RTS, RAPADILINO Syndrome and Baller-Gerold Syndrome." (PMID 25859855, 2015). "Interestingly, mutations within RECQL4 gene are linked to three distinct autosomal recessive conditions with overlapping phenotypes, i.e. Rothmund-Thomson, RAPADILINO, and Baller-Gerold syndrome (BGS), but only the last disorder comprises hearing loss in its clinical spectrum." (PMID 32139749, 2020). "Furthermore, fetal valproate exposure has been reported to cause other malformation complexes such as Baller-Gerold syndrome (BGS, OMIM #218600), an ultra-rare disorder caused by pathogenic variants in the RECQL4 gene on chromosome 8p24, and inherited in an autosomal recessive manner." (PMID 33959609, 2021).
prostate carcinoma (17 papers, 2013 to 2025). A carcinoma that arises from epithelial cells of the prostate gland. "Elevation of RECQL4 level was positively associated with the aggressiveness of prostate cancer both in vitro and in vivo, implying that RECQL4 plays critical roles in prostate-cancer carcinogenesis and is a valuable biomarker for this cancer." (PMID 33628589, 2021). "RECQL4 depletion in oxaliplatin-resistant colon adenocarcinoma and prostate cancer decreased oncogenic behaviors." (PMID 40196015, 2025). "Elevations in RECQL4 display oncogenic activities in prostate cancer and promote chemoresistance in gastric cancer." (PMID 35681785, 2022). "A study demonstrated that RECQL4 inhibition in prostate cancer cells led to significant reduction in invasive growth in vitro and tumorigenic potential in vivo." (PMID 35782872, 2022). "Upregulated RECQL4 expression has been found to correlate with increased tumor aggressiveness in human prostate cancer cells." (PMID 35782872, 2022). "Consistent with promotion of tumor cell growth, RECQL4 overexpression is correlated with tumor aggressiveness in breast and prostate cancer and its suppression results in reduced proliferation." (PMID 34946868, 2021). "Recent studies have shown that RECQL4 overexpression occurs in prostate cancer, sporadic osteosarcoma, sporadic breast cancer, colorectal cancer, liver cancer, and gastric cancer, and is significantly associated with clinical outcomes." (PMID 33628589, 2021). "Knockdown of RECQL4 with short hairpin (sh) RNA in breast and prostate cancer cells increased spontaneous DNA strand breaks, reduced cell survival in vitro and tumour growth in vivo." (PMID 33050631, 2020). "Elevations in RecQL4 display oncogenic activities in prostate cancer and promote chemoresistance in gastric cancer; evidence thus supports the important roles of RecQL4 in promoting tumorigenesis." (PMID 33266355, 2020). "Elevated RecQL4 expression observed in different human cancers has been demonstrated to correlate with tumorigenic potential in both breast and prostate cancer cells, and cisplatin resistance in gastric cancer cells." (PMID 30206236, 2018). "In fact, RECQL4-depleted prostate cancer cells undergo extensive apoptotic death in PARP -1-dependently in vitro and show reduced tumorigenicity in nude mice in vivo." (PMID 25620975, 2014). "Additionally, the histone deacetylase inhibitor trichostatin A led to suppression of RECQL4 in prostate cancer cells." (PMID 39812592, 2025). "While it is unclear whether RECQL4 expression in cancer cells is related to radiation resistance, a preliminary study showed that RECQL4 inhibition enhanced radiation sensitivity of prostate cancer cells." (PMID 35782872, 2022). "Specifically, another important observation, discovered already in the previous study on prostate cancer, was that RECQL4 may be a new biomarker for advanced prostate cancer due to its increase in metastatic prostate cancer cells and tumor tissues." (PMID 34486474, 2021). "Expression of RECQL4 is elevated in certain cancer cells, breast and prostate cancer tissues." (PMID 33050631, 2020). "Because the expression of RECQL4 increased highly in metastatic prostate cancer cells and in tumor tissue, RECQL4 protein could be used as new tumor marker." (PMID 25620975, 2014). "Strikingly, in a prostate cancer focused study, suppressing RECQL4 to levels observed in non-malignant human epithelial cells is sufficient to reduce invasive growth and tumorigenic potential." (PMID 34946868, 2021).
rapadilino syndrome (17 papers, 2012 to 2025). "While some mutations in RECQL4 also lead to loss of protein, both missense mutations and the deletion of exon 7 common in RAPADILINO syndrome stand in contrast to the truncations of WRN and BLM." (PMID 23238538, 2012). "Later, based on a clinical overlap between RAPADILINO syndrome and RTS, the Finnish individuals were screened for variants in RECQL4 and the identification of biallelic variants in these individuals showed that RAPADILINO and RTS were allelic conditions." (PMID 38021400, 2023). "Mutations in RECQL4 are associated with three genetic disorders, Rothmund–Thomson syndrome (RTS), Baller–Gerold syndrome (BGS), and RAPADILINO syndrome." (PMID 33718381, 2021). "Homozygous (or compound heterozygous) germline mutations in the RECQL4 gene have been associated with Rothmund-Thompson (RTS), Baller-Gerold (BGS), and RAPADILINO syndromes." (PMID 33541411, 2021). "Mutations in RecQL4 results in three autosomal recessive disorders: RTS, RAPADILINO syndrome, and BGS4." (PMID 30206236, 2018). "Unlike RTS and BGS, RAPADILINO syndrome is solely caused by mutations in the RECQL4 gene." (PMID 40728512, 2025).
gastric cancer (15 papers, 2018 to 2025). A primary or metastatic malignant neoplasm involving the stomach. "Overexpression of RECQL4 in more than half of the seven gastric cancer cell lines analyzed, were not only associated with poor prognosis but also with enhanced resistance to cisplatin via the downstream AKT-YB1-MDR1 signaling pathway." (PMID 35782872, 2022). "Higher RECQL4 expression was observed in gastric cancers, and RECQL4 protein levels were associated with poor survival of gastric cancer patients." (PMID 33628589, 2021). "RECQL4 has also been shown to be associated with cisplatin resistance in gastric cancer by activating AKT26." (PMID 33628589, 2021). "In the TCGA cohort, gastric cancer (GC) harboring variants in RECQL4, ARID1A, MAGI1, or JAK3 were 4.5% (n = 20), 27.0% (n = 119), 7.5% (n = 33), or 3.8% (n = 17), respectively." (PMID 33328548, 2020). "Several studies have indicated that RECQL4 is associated with cancer progression and may be a diagnostic marker for cancer, e.g., the overexpression of RECQL4 is associated with a poor prognosis of gastric cancer and predicts poor prognosis in hepatocellular carcinoma." (PMID 34361106, 2021). "Similar to esophageal and ovarian cancers, RECQL4 mRNA expression was also increased in human gastric cancer and hepatocellular carcinoma cells, correlating with poor prognosis." (PMID 35782872, 2022). "In the setting of elevated endogenous RECQL4, silencing of ectopic RECQL4 in cisplatin-resistant gastric cancer cells led to reduced activation of this pathway and subsequent resensitization to cisplatin." (PMID 35782872, 2022). "Gastric cancer cells with enhanced RECQL4 expression correlated with more extensive invasion, as compared with normal gastric mucosa cells." (PMID 35782872, 2022). "This decision was made because previous studies in humans have reported that RECQL4 mRNA is upregulated in hepatocellular carcinoma tissues and gastric cancer tissues." (PMID 35632763, 2022). "RECQL4 mRNA was upregulated in gastric cancers and RECQL4 depletion reduced cell proliferation and induced growth arrest." (PMID 33050631, 2020). "For example, high expression of RECQL4 in HCC or TRIM6 in microsatellite-stable gastric cancer potently suppresses the cGAS-STING pathway, leading to poor T-cell infiltration and likely blunting the response to ablation-driven vaccination without additional targeted modulation." (PMID 41295487, 2025). "While our retrospective analysis demonstrated that RECQL4 levels correlate with increased response to cisplatin, it should be noted that multiple studies demonstrated that high levels of RECQL4 results in resistance to cisplatin in other cancer types including breast and gastric cancer cell lines." (PMID 36126066, 2022). "We also found six genes in MSS tumors (EYS, FAT4, FSIP2, PCDHA1, RAD50, and RECQL4) and two in MSI tumors (EXO1 and FSIP2) that were clonally mutated in multiple patients and have not been previously identified as drivers of gastric cancer or other cancers." (PMID 36970058, 2022).
ovarian carcinoma (12 papers, 2016 to 2025). A malignant neoplasm originating from the surface ovarian epithelium. "RECQL4 was found to be upregulated and associated with a poor prognosis based on the immunohistochemistry staining of ovarian cancer." (PMID 33014878, 2020). "Finally, we found that germline deleterious mutations in FANCD2 and RECQL4 were likely susceptibility genes for ovarian cancer, and we should be more cautious to these two genes." (PMID 38509102, 2024). "Furthermore, RECQL4 amplification is observed in 20–30% of ovarian cancer and high RECQL4 expression is associated with a poor prognosis in ovarian cancer." (PMID 35267530, 2022). "The overexpression of RECQL4 in ovarian cancer patients was associated with poor clinical outcomes." (PMID 33014878, 2020). "Thus, RECQL4 deleterious mutations, especially the mutation c.212A > G may predispose carriers to ovarian cancer." (PMID 38509102, 2024). "Furthermore, we pointed out that deleterious mutations of FNACD2 and RECQL4 are potential ovarian cancer susceptibility genes and may predispose carriers to ovarian cancer." (PMID 38509102, 2024). "In addition to the known ovarian cancer high-risk genes, we found that germline mutations in FANCD2 and RECQL4 may be associated with hereditary and early onset of ovarian cancer." (PMID 38509102, 2024). "Except for ovarian cancer and melanoma, analyses of the individual cancer cohorts revealed the dominance of RECQL4 high amplification in metastatic samples over primary tumour tissues (p < .05)." (PMID 39812592, 2025). "When ovarian cancer tissues were examined, upregulation of RECQL4 positively correlated with enhanced cell proliferation and invasion relating to potential worse survival." (PMID 35782872, 2022). "PARP10 amplification co-occurred with RECQL4 amplification, both located on Chr 8q24.3, in both cell lines and ovarian cancers (TCGA)." (PMID 33804647, 2021). "For instance, in ovarian cancer, RECQL4 can be negatively regulated by miR-10a-5p, thereby promoting cell proliferation and invasion." (PMID 34486474, 2021). "RECQL4 pathogenic mutations were only detected in Asian (Chinese) patients in our study, and RECQL4 c.C2272T has been reported in ovarian cancer/Rothmund–Thomson syndrome." (PMID 33889545, 2021). "Together, these data suggest that the MAFB is involved in RECQL4-mediated oncogenic behavior of ovarian cancer cells." (PMID 33014878, 2020). "Ovarian cancer cells were treated with different concentrations of cisplatin for 48 h, and RECQL4 protein expression increased in a dose-dependent manner." (PMID 33014878, 2020). "A transwell assay was then conducted to investigate the effect of RECQL4 on ovarian cancer cell invasion." (PMID 33014878, 2020). "Correlation analysis between RECQL4 expression and clinicopathologic characteristics of ovarian cancer patients based on immunohistochemistry staining." (PMID 33014878, 2020). "The effect of RECQL4 knockdown on the apoptosis of ovarian cancer cells was evaluated by Flow cytometry." (PMID 33014878, 2020). "CCK-8 assays showed that the IC50 of cisplatin in ovarian cancer cells declined after RECQL4 knockdown." (PMID 33014878, 2020). "In this study, we demonstrated that RECQL4 overexpression promoted the growth, clone formation, and invasion of ovarian cancer cells In contrast, RECQL4 knockdown reduced cell proliferation and invasion capacity." (PMID 33014878, 2020). "This is the first study to reveal the oncogenic functions and clinical significance of RECQL4 in ovarian cancer." (PMID 33014878, 2020). "RECQL4 expression was significantly upregulated in ovarian cancer tissues when compared to normal FT tissues." (PMID 33014878, 2020). "Here, we studied the expression, biological functions, and clinical significance of RECQL4 in ovarian cancer, and the reasons for high expression of RECQL4 were further analyzed in this study." (PMID 33014878, 2020).
ovarian carcinoma (continued). "High levels of RECQL4 mRNA expression were also found to be positively related with its CNV in the ovarian cancer cell line using data from the CCLE dataset." (PMID 33014878, 2020). "Kaplan–Meier analysis revealed that ovarian cancer patients with high RECQL4 expression had reduced overall survival (OS)." (PMID 33014878, 2020). "We further evaluated the role of RECQL4 in enhancing the sensitivity of ovarian cancer cells to olaparib." (PMID 33014878, 2020). "Based on the microRNA expression in ovarian cancer tissues, miR-10a-5p expression was found to be downregulated in ovarian cancer compared with fresh-frozen FT tissues, so it was considered a potential functional regulator of RECQL4." (PMID 33014878, 2020). "Taken together, these data elucidate a novel miR-10a-5p/RECQL4/MAFB axis that regulates the biological functions of ovarian cancer cells." (PMID 33014878, 2020). "Taken together, these data show that ovarian cancer cells with RECQL4 knocked down are more sensitive to cisplatin and olaparib treatment than control cells." (PMID 33014878, 2020). "Here, using bioinformatics analysis, RECQL4 amplification was found to occur in 27% of ovarian cancer samples in the TCGA cohort." (PMID 33014878, 2020). "Accordingly, these results indicated that RECQL4 overexpression increases the invasion of ovarian cancer cells." (PMID 33014878, 2020). "In conclusion, our results revealed that RECQL4 amplification and miR-10a-5p suppression resulted in high RECQL4 expression in ovarian cancer." (PMID 33014878, 2020). "In this study, RECQL4 was found to be significantly increased in cisplatin-resistant ovarian cancer cell lines, while knockdown conveyed higher sensitivity to cisplatin." (PMID 33014878, 2020). "Collectively, these findings indicate that genomic amplification and low expression of miR-10a-5p contribute to RECQL4 overexpression in ovarian cancer." (PMID 33014878, 2020). "Ovarian cancer patients treated with cisplatin with high RECQL4 expression had shorter OS than those with low RECQL4 expression according to the online analysis website Kaplan–Meier Plotter." (PMID 33014878, 2020). "qRT-PCR was applied to assess the relative expression of RECQL4 between ovarian cancer and FT tissues." (PMID 33014878, 2020). "RECQL4 expression was found to be higher in ovarian cancer tissues than in normal tissues in the GSE12470 and GSE26712 datasets." (PMID 33014878, 2020). "In our study, germline deleterious mutations in RECQL4 were significantly associated with a family history in patients without BRCA1/2 mutations, suggesting that it may be also related to ovarian cancer susceptibility." (PMID 38509102, 2024). "RECQL4 depletion led to increased sensitivity of the ovarian cancer cells to cisplatin and olaparib, a PARP inhibitor, which suggests that RECQL4 may be a critical component in the resistance of ovarian malignant cells to cisplatin." (PMID 35782872, 2022). "RECQL4 can be used as a potential prognostic marker and a novel drug target for ovarian cancer." (PMID 33014878, 2020). "Moreover, RECQL4 was amplified in approximately 27% of ovarian cancer cases, and its amplification was correlated with high mRNA levels." (PMID 33014878, 2020). "In addition, RECQL4 knockdown enhanced the sensitivity of ovarian cancer cells to cisplatin and PARP inhibitor (PARPi)." (PMID 33014878, 2020). "MAFB mRNA expression positively correlated with RECQL4 expression in ovarian cancer tissues." (PMID 33014878, 2020). "In addition, RECQL4 protein expression levels in ovarian cancer cells was markedly higher than it was in the normal FT cell line FTE187." (PMID 33014878, 2020). "RECQL4 mRNA and protein expression levels were decreased following transfection with miR-10a-5p mimics, while treatment with an inhibitor increased the expression of RECQL4 in ovarian cancer cells." (PMID 33014878, 2020). "RECQL4 mRNA expression was significantly upregulated in ovarian cancer." (PMID 33014878, 2020).